CIDEC (cell death inducing DFFA like effector c)
Description:
Lipid transferase specifically expressed in white adipose tissue, which promotes unilocular lipid droplet formation by mediating lipid droplet fusion. Lipid droplet fusion promotes their enlargement, restricting lipolysis and favoring lipid storage. Localizes on the lipid droplet surface, at focal contact sites between lipid droplets, and mediates atypical lipid droplet fusion by undergoing liquid-liquid phase separation (LLPS) and promoting directional net neutral lipid transfer from the smaller to larger lipid droplets. The transfer direction may be driven by the internal pressure difference between the contacting lipid droplet pair. Its role in neutral lipid transfer and lipid droplet enlargement is activated by the interaction with PLIN1. May also act as a CEBPB coactivator in the white adipose tissue to control the expression of a subset of CEBPB downstream target genes, including SOCS1, SOCS3, TGFB1, TGFBR1, ID2 and XDH (By similarity). When overexpressed in preadipocytes, induces apoptosis or increases cell susceptibility to apoptosis induced by serum deprivation or TGFB treatment.
Synonyms: FSP27; CIDE-3; FLJ20871; CIDE3; FPLD5
Tractability: PROTAC: UniProt records ubiquitination sites on it.
Gene: Protein-coding gene on chromosome 3 (9,866,710 to 9,880,256, reverse strand). Ensembl gene ENSG00000187288.
Subcellular location: Lipid droplet; Endoplasmic reticulum; Nucleus
Pathways (Reactome):
Gene expression (Transcription): MLL4 and MLL3 complexes regulate expression of PPARG target genes in adipogenesis and hepatic steatosis
Metabolism: Lipid particle organization
Transport of small molecules: Assembly of active LPL and LIPC lipase complexes
Gene Ontology:
Molecular function: protein binding; lipid transfer activity; molecular condensate scaffold activity; phosphatidic acid binding
Biological process: apoptotic process; execution phase of apoptosis; lipid droplet fusion; lipid droplet organization; lipid storage; negative regulation of lipid catabolic process; negative regulation of triglyceride metabolic process; intermembrane lipid transfer
Cellular component: cytosol; lipid droplet; endoplasmic reticulum; nucleus
Genetic constraint (gnomAD): Loss-of-function variants: 13 observed, 22.3 expected, observed/expected ratio (o/e) 0.58, 90% interval 0.38 to 0.93. The upper end of that interval is the gene's LOEUF score, 0.93, which puts it in group 3 of 6, group 1 being the genes least tolerant of losing a copy. Missense variants: 296 observed, 292.95 expected, observed/expected ratio (o/e) 1.01, 90% interval 0.92 to 1.11. Synonymous variants: 126 observed, 118.1 expected, observed/expected ratio (o/e) 1.07, 90% interval 0.92 to 1.24.
Homologues: Orthologues: chimpanzee CIDEC (100% identical), macaque CIDEC (96% identical), dog CIDEC (86% identical), pig CIDEC (84% identical), mouse Cidec (80% identical), rat Cidec (80% identical), guinea pig CIDEC (79% identical), rabbit CIDEC (77% identical), tropical clawed frog cidec (61% identical), zebrafish cidec (48% identical), Drosophila melanogaster Drep2 (30% identical). Paralogues in human: CIDEA (41% identical), CIDEB (38% identical), DFFA (21% identical).